MIR5585 (microRNA 5585)
Synonyms: hsa-mir-5585
Gene: MicroRNA gene on chromosome 1 (32,086,949 to 32,087,007, forward strand). Ensembl gene ENSG00000266203.
Homologues: Orthologues: chimpanzee MIR5585 (100% identical).